GDF15 (growth differentiation factor 15)
Diseases named in the same sentence as GDF15 in open-access papers (continued):
Sharing a sentence is not in itself a finding about the gene and the disease.
gallstones (1 paper, 2022). Solid crystalline precipitates in the biliary tract, usually formed in the gallbladder, resulting in the condition of cholelithiasis. "An experiment in mice found that metformin that elevates circulating GDF-15 levels reduced the risk of gallstones induced by a high-fat diet." (PMID 35769993, 2022). "In this first study on GDF-15 in relation to gallstones, we found an association between genetically predicted GDF-15 levels and the risk of gallstone disease." (PMID 35769993, 2022). "Therefore, we conducted a two-sample Mendelian randomization (MR) study and polygenic risk score analysis, here, to determine the association between genetically predicted GDF-15 levels, a biomarker of metformin use, and the risk of gallstones." (PMID 35769993, 2022). "Our study found that genetically predicted GDF-15 levels were significantly associated with gallstones, which support our hypothesis." (PMID 35769993, 2022). "Four GDF-15–associated SNPs showed consistent associations with gallstones in FinnGen." (PMID 35769993, 2022). "However, this pleiotropy was supposed to generate a limited impact on our findings since this SNP explains a small variance in GDF-15 levels, and the observed association between GDF-15 and gallstones was mainly driven by rs1227734 located in the GDF15 gene region." (PMID 35769993, 2022). "In conclusion, this MR study suggests a detrimental effect of high GDF-15 levels on gallstone formation for the first time." (PMID 35769993, 2022). "Taken together, our findings implied a possible adverse outcome, gallstones, when considering GDF-15 as a potential therapeutic target for diabetic complications." (PMID 35769993, 2022). "In addition, GDF-15 may be a proxy for immobilization, impaired fasting glucose, and insulin resistance, which are risk factors for the development of gallstones." (PMID 35769993, 2022). "In the two-sample MR analysis, the odds ratio (OR) of gallstones was 1.09 (95% confidence interval (CI), 1.03–1.15; p = 0.001) for one standard deviation increase in genetically predicted GDF-15 levels in the meta-analysis of two datasets." (PMID 35769993, 2022). "In stratification analysis, the significant association between higher genetically predicted GDF-15 and gallstones was only observed in nondiabetic individuals." (PMID 35769993, 2022). "Linear and nonlinear associations between genetically predicted GDF-15 levels and gallstones were estimated with stratification by the diabetic status." (PMID 35769993, 2022).
gastritis (1 paper, 2016). Inflammation of the stomach. "Serum levels of GDF15 were significantly higher in DGC patients (mean ± SD, 1,159 ± 579 pg mL−1) as compared with healthy volunteers (383 ± 110 pg mL−1) and gastritis patients (855 ± 360 pg mL−1)." (PMID 26892343, 2016). "Serum GDF15 levels were significantly higher in DGC patients than in both healthy individuals and gastritis patients, and positively correlated with wall invasion and lymph node metastasis." (PMID 26892343, 2016).
Glomerular sclerosis (1 paper, 2018). Accumulation of scar tissue within the glomerulus. "In our study, PLA2R Ab showed a positive correlation with glomerular sclerosis and GDF-15." (PMID 29682097, 2018).
GNE myopathy (1 paper, 2022). "Serum GDF15, as well as NCAM1, elevation in GNE myopathy likely results from expression by regenerating muscle fibres during the process of progressive degeneration of the overall tissue." (PMID 35148379, 2022). "While GDF15 levels can still be used to effectively distinguish CMT from GNE myopathy, there was a significant elevation of GDF15 within the GNE myopathy cohort compared to controls." (PMID 35148379, 2022).
Headache (1 paper, 2021). Cephalgia, or pain sensed in various parts of the head, not confined to the area of distribution of any nerve. "A cross-sectional study in two headache centers was conducted analyzing GDF-15 and FGF-21 serum concentration in 230 patients with episodic and chronic migraine compared to a control group." (PMID 34572118, 2021). "With increasing average headache intensity, serum concentrations of both FGF-21 and GDF-15 were slightly higher." (PMID 34572118, 2021).
hemoglobinopathies (1 paper, 2018). "These include erythroferrone produced by erythroblasts in response to erythropoeitic stress, as well as other mechanisms, including growth differentiation factor 15 (GDF-15), which is seen mainly in patients with hemoglobinopathies." (PMID 29342861, 2018).
hip fracture (1 paper, 2024). Traumatic or pathological injury to the hip in which the continuity of either the femoral head, femoral neck, intertrochanteric or subtrochanteric regions is broken. "Thus, the possibility that high GDF15 levels may be a risk factor for a hip fracture needs further investigation." (PMID 39668628, 2024).
Huntington disease (1 paper, 2024). Huntington disease (HD) is a rare neurodegenerative disorder of the central nervous system characterized by unwanted choreatic movements, behavioral and psychiatric disturbances and dementia. "In fact, one study showed silencing GDF15 was protective in a drosophila model of Huntington’s disease, by ameliorating endoplasmic reticulum-stress induced apoptosis in photoreceptors." (PMID 39737171, 2024).
hydronephrosis (1 paper, 2026). Collection of urine in the renal pelvis that results in dilatation of the renal pelvis and calyces. "Urine and serum GDF-15 levels demonstrated variation according to stone location, hydronephrosis grade, and ureteral wall thickness." (PMID 41515626, 2026).
hyperandrogenism (1 paper, 2024). Excessive secretion of androgens from the adrenal glands or gonads. "Therefore, in women with PCOS, increased GDF-15 levels could reduce hyperandrogenism – the main characteristic of the disease – but the GDF-15 effects on ovulation should be further investigated." (PMID 39420932, 2024).
hypercoagulable (1 paper, 2026). "Although the hypercoagulable state is recognized as a biological mechanism that triggers cardiac events in CAD, the relationship between GDF-15 and coagulation parameters in patients with CAD remains unclear." (PMID 41659098, 2026).
hyperferritinemia (1 paper, 2022). "The enhancement of ferroportin-mediated iron efflux by growth differentiation factor 15 (GDF15) appears to be involved in the modulation of iron homeostasis and the development of hyperferritinemia in HLH." (PMID 35629101, 2022).
hyperlipemia (1 paper, 2016). "However, plasma GDF-15 levels were insignificantly in patients with hyperlipemia (1340.4 ± 694.4 ng/l vs. 1528.5 ± 852.7 ng/l, P = 0.41)." (PMID 27311391, 2016).
Hyponatremia (1 paper, 2025). An abnormally decreased sodium concentration in the blood. "In addition, growth differentiation factor-15 (GDF-15) and lactate, creatinine, hyponatremia, and even copeptin, a surrogate marker of antidiuretic hormone, have also been found to be used for risk stratification in patients with APE, and these factors need further validation." (PMID 40672378, 2025).
hypoplastic left heart syndrome (1 paper, 2022). Hypoplastic left heart syndrome (HLHS) refers to the abnormal development of the left-sided cardiac structures, resulting in obstruction to blood flow from the left ventricular outflow tract. "Therefore, the aim of this study was to evaluate the effects of an aerobic exercise program on cardiopulmonary exercise testing and cardiac biomarkers (hs-cTnT, NT-proBNP, ST2 and GDF-15) in adult patients with Hypoplastic Left Heart Syndrome (HLHS) and Fontan circulation." (PMID 35735800, 2022).
idiopathic dilated cardiomyopathy (1 paper, 2021). Decreased function of the heart associated with cardiac enlargement and congestive heart failure, of unknown cause. "In another recent study, Nair and Gongora analyzed the correlations of GDF-15 with worsening functional capacity as well as the interactions between GDF-15 and other markers of fibrosis, in patients with idiopathic dilated cardiomyopathy." (PMID 34073616, 2021).
influenza (1 paper, 2023). An acute viral infection of the respiratory tract, occurring in isolated cases, in epidemics, or in pandemics; it is caused by serologically different strains of viruses (influenzaviruses) designated A, B, and C, has a 3-day incubation period, and usually lasts for 3 to 10 days. "While influenza cases were primarily characterized by pro-inflammatory signaling and classical anti-viral response gene expression (e.g., BCL6, DLL4, GDF15, PTX3,HMGB2, and IL-8)." (PMID 36371548, 2023).
intestinal cancer (1 paper, 2025). "For example, the expression of NAG-1/GDF15 in a standard mouse model (Apc-Min) for intestinal cancer suppressed the formation of intestinal neoplasia, providing evidence for in vivo tumor suppressor activity." (PMID 40316530, 2025).
intestinal polyp (1 paper, 2021). Discrete abnormal tissue masses that protrude into the lumen of the intestine. "Its activation has been linked with a reduced propensity to develop intestinal polyps and tumors in mice, which, combined with its expression being regulated by NSAIDs, evoke an interest in NAG1/GDF-15/MIC-1 as a chemopreventive agent." (PMID 34885960, 2021).
intestinal tumors (1 paper, 2013). "Transgenic mice expressing human NAG-1/GDF15 (NAG-1Tg/Lox) are leaner with lower body weight and are resistant to chemically or genetically induced intestinal tumors." (PMID 23737651, 2013).
intracranial hemorrhage (1 paper, 2021). Bleeding within the SKULL, including hemorrhages in the brain and the three membranes of MENINGES. "The relationships between GDF-15 and risk of intracranial hemorrhages, ICH or SAH were not separately evaluated in those studies." (PMID 34177769, 2021).
iron metabolism disorders (1 paper, 2025). "In this context, growth differentiation factor-15 (GDF-15) has emerged as a promising biomarker for monitoring iron metabolism disorders and treatment response." (PMID 41446860, 2025).
kidney stone (1 paper, 2021). "After adjusting for history of kidney stone (395 cases out of 4309 subjects), the adjusted HR was 2.40 (95% CI, 1.34 ~ 4.29) for Q4 versus Q1 of GDF-15 (p for trend < 0.01), and was 1.39 (95% CI, 1.16 ~ 1.65) for each 1 SD increase in GDF-15 (data not shown)." (PMID 34706669, 2021).
large bowel polyps (1 paper, 2015). "Development of large bowel polyps and cancer in Apcmin mice is reduced by transgenic overexpression of MIC-1/GDF15." (PMID 25695521, 2015).
laryngeal squamous cell carcinoma (1 paper, 2025). A squamous cell carcinoma that arises from the larynx. "The significant association between high GDF15 expression and poorer overall survival in patients with laryngeal squamous cell carcinoma, predominantly observed in the tissue microarray (TMA) dataset, may suggest the potential prognostic value of this protein." (PMID 40725563, 2025). "Previous studies evaluating GDF15 as a marker for malignant tumors and metastasis diagnosis prompted us to investigate its expression in patients with laryngeal squamous cell carcinoma (LSCC)." (PMID 40725563, 2025). "Future studies with larger cohorts and more robust event data are necessary to validate our findings and provide more comprehensive insights into the role of GDF15 as a prognostic biomarker for laryngeal squamous cell carcinoma." (PMID 40725563, 2025). "Moreover, GDF15 expression is correlated with decreased survival in cancer patients, particularly in laryngeal squamous cell carcinoma, highlighting its potential prognostic value." (PMID 40725563, 2025). "However, the role of GDF15 in laryngeal squamous cell carcinoma remains unexplored." (PMID 40725563, 2025).
limited systemic sclerosis (1 paper, 2025). "Three biomolecules proposed as biomarkers for differentiating between diffuse and limited systemic sclerosis are produced by progenitor myelopoietic cells (SuPAR), the muscle of the left atrium of the heart (MR-proANP), and macrophages (GDF-15)." (PMID 40362179, 2025).
liposarcoma (1 paper, 2024). A usually painless malignant tumor that arises from adipose tissue. "Consistently with in vitro results, the presence of released GDF-15 was observed to a variable extent in the blood of a panel of mice carrying EHE xenotransplants of different size but not in healthy mice and in those carrying pleomorphic liposarcoma xenotransplants." (PMID 39283723, 2024).
lumbar disc degeneration (1 paper, 2024). "Some genes are widespread in chondrocyte 4, and chondrocyte 5 may play an important role in the process of lumbar disc degeneration together with the Wnt/Ca2+signaling pathway, such as ANGPTL4, PTGES, IGFBP3, GDF15, TRIB3, and TNFRSF10B." (PMID 38654287, 2024). "ANGPTL4, IGFBP3, PTGES in chondrocytes 4 and TRIB3, GDF15, TNFRSF10B in chondrocytes 5 may play an important role in the lumbar disc degeneration process." (PMID 38654287, 2024).
lymphedema (1 paper, 2021). Excess fluid collection in tissues, causing swelling. "Nevertheless, preadipocytes derived from lymphedema subjects exhibited differential expression of GDF15, the marker of mitochondrial stress, and of KLF4, KLF6, INHBA and ZNF423, i.e. genes implicated in adipogenesis, when compared with cells from healthy women." (PMID 33854130, 2021).
male infertility (1 paper, 2025). The inability of the male to effect fertilization of an ovum after a specified period of unprotected intercourse. "Collectively, our findings highlight an essential role of APBB1/KAT5/GDF15 in governing human SSC fate decisions and maintaining normal spermatogenesis and underscore them as therapeutic targets for treating male infertility." (PMID 40151319, 2025).
malignant neoplasm of respiratory system (1 paper, 2022). "Other tested endpoints (psychiatric disorders; malignant neoplasm of respiratory system and intrathoracic organs) also showed similar results for which plasma GDF15 levels seemed to predict the disease." (PMID 35916366, 2022).
meningioma (1 paper, 2025). A generally slow growing tumor attached to the dura mater. "In meningiomas, GDF15 gene expression was significantly associated with tumour grade and the Ki-67 Pi." (PMID 41009755, 2025). "In meningioma patients, the expression levels of DJ-1, GDF15, and MFGE8 genes were elevated in tumours larger than 3 cm compared to smaller tumours and the control group." (PMID 41009755, 2025). "In meningioma patients, the expression levels of the DJ-1, GDF15, and MFGE8 genes were significantly higher in Grade II tumours compared to Grade I tumours." (PMID 41009755, 2025). "In meningioma patients, DJ-1, GDF15, and MFGE8 gene expression levels were significantly elevated in tumours with Ki-67 Pi > 5% compared to those with Ki-67 Pi ≤ 5% (DJ-1, GDF15, and MFGE8; p = 0.015, p = 0.003, and p = 0.012, respectively)." (PMID 41009755, 2025). "ROC analyses for meningioma cases revealed that the AUC values for these genes were all below 0.7, with p-values above 0.05, indicating that DJ-1, GDF15, and MFGE8 do not have sufficient diagnostic discriminatory power based on patient sex in meningioma." (PMID 41009755, 2025). "ROC analyses showed that the AUC values for DJ-1 and GDF15 were below 0.7, with p-values above 0.05, whereas the MFGE8 gene demonstrated an AUC value above 0.7 with a p-value below 0.05, indicating that only MFGE8 has potential diagnostic discriminatory power for tumour diameter in meningioma." (PMID 41009755, 2025). "The expression levels of the DJ-1, GDF15, and MFGE8 genes in meningioma patients were elevated compared to those in the control group." (PMID 41009755, 2025). "Therefore, examining gene expression levels across these subgroups may offer a framework for assessing the potential of DJ-1, GDF15, and MFGE8 to discriminate between benign and atypical meningiomas and their possible functional roles in tumour biology." (PMID 41009755, 2025).
metastasis (1 paper, 2021). The spread or migration of cancer cells from one part of the body (where they first appeared) to another. "Serum GDF-15 levels and multiple protein expressions in lysates extracted from liver metastasis were measured by enzyme-linked immuno-sorbent assay and reverse-phase protein array, respectively." (PMID 34638326, 2021).
mitochondrial DNA depletion syndrome (1 paper, 2022). The mitochondrial DNA (mtDNA) depletion syndrome (MDS) is a clinically heterogeneous group of mitochondrial disorders characterized by a reduction of the mtDNA copy number in affected tissues without mutations or rearrangements in the mtDNA. "It is worth mentioning that GDF15 has been recently reported to be increased in patients with genetic mitochondrial DNA diseases, including mitochondrial DNA depletion syndromes." (PMID 35160008, 2022).
myelodysplastic syndrome (1 paper, 2015). A clonal hematopoietic disorder characterized by dysplasia and ineffective hematopoiesis in one or more of the hematopoietic cell lines. "In hematopoietic diseases, serum GDF15 levels are remarkably elevated in patients with dyserythropoietic disorders such as β-thalassemia, congenital dyserythropoietic anemia type I, and refractory anemia with ring sideroblasts, a subtype of myelodysplastic syndromes (MDS) 14–17." (PMID 26276681, 2015).
myopia (1 paper, 2025). "Additionally, growth differentiation factor 15 (GDF-15), hepatocyte growth factor (HGF), and platelet-derived growth factor (PDGF)-AA were also significantly elevated in the aqueous humor in high myopia patients, indicating novel biomarkers for myopia progression." (PMID 41191163, 2025).
myxoma (1 paper, 2024). A benign soft tissue neoplasm characterized by the presence of spindle and stellate cells, lobulated growth pattern, and myxoid stroma formation. "The hyperactive signals in many malignant tumours, such as MDK, HGF, chemerin and GDF15 signalling, were found to be sent primarily by myxoma tumour cells." (PMID 38318640, 2024).
Nausea (1 paper, 2024). A sensation of unease in the stomach together with an urge to vomit. "Because increased GDF15–GFRAL signalling is associated with nausea, these data also suggest that nausea may be driving, at least in part, the reduction in food intake after pharmacologically mediated increases in N-acetyltaurine." (PMID 39112712, 2024).
nephrosis (1 paper, 2024). Pathological processes of the KIDNEY without inflammatory or neoplastic components. "Furthermore, PAN-induced renal injury in Gdf15 knockout mice exhibited elevated glomerular immune cell infiltration alongside a phenotype of PAN-induced nephrosis as compared with wild-type mice." (PMID 38607075, 2024).
neuroblastoma (1 paper, 2017). Neuroblastoma (NB) is the most common solid, extracranial childhood tumor. "On the other hand neuroblastoma cells which entered the cell death pathway are characterized by activation of EGR1, VEGF, and GDF15." (PMID 29362714, 2017).
Neuromyelitis Optica Spectrum disorder (1 paper, 2024). "Research examining serum GDF15 in individuals with Neuromyelitis Optica Spectrum disorder, a demyelinating autoimmune condition akin to MS, was also included in this review." (PMID 39737171, 2024).
neuropathic pain (1 paper, 2016). Chronic pain caused by damage to nerve fibers. "Of the 47 investigated proteins, 21 (cathepsin S, CCL2, CCL4, CCL16, CFIII, CXCL5, cystatin B, E-Selectin, Fas/TNFRSF6, follistatin, GDF-15, GH, ICAM1, IL8, KLK5, MMP2, MMP9, P-Selectin, sortilin, TIMP4 and VEGF) were detectable by multiplex SP-PLA in ≥ 95% of the neuropathic pain patient samples." (PMID 26914813, 2016).
non-squamous non-small cell lung cancer (1 paper, 2025). "Recently research has shown that Visugromab, a GDF15 neutralizing antibody, can improve efficacy of anti-PD-1-based cancer immunotherapy in non-squamous non-small cell lung cancer, urothelial cancer, and potentially HCC, highlighting its clinical relevance." (PMID 40677718, 2025).